CKAP2L (cytoskeleton associated protein 2L)
Diseases named in the same sentence as CKAP2L in open-access papers (continued):
Sharing a sentence is not in itself a finding about the gene and the disease.
tumor (continued). "However, it is confusing that M1 macrophages, which are antitumor, are positively correlated with CKAP2L expression, and M2 macrophages, which have pro-tumor activity, are negatively correlated with CKAP2L expression." (PMID 37225919, 2023). "In tumor tissues, CKAP2L expression was significantly higher than in normal tissues." (PMID 37225919, 2023). "Furthermore, CKAP2L expression was positively associated with neutrophils and MDSC, they are both immune cells with pro-tumor activities." (PMID 37225919, 2023). "And the expression of CKAP2L in tumor tissue increases with the TMN stage of the tumor." (PMID 37225919, 2023). "But until now, there are few studies focused on the relationship between CKAP2L and tumor immunity." (PMID 37225919, 2023). "In vivo, silencing CKAP2L significantly inhibited the tumor growth rates and final weights." (PMID 35715760, 2022). "The CKAP2L expression patterns in tumor and adjacent normal were significantly different." (PMID 35715760, 2022). "In brief, we identified CKAP2L as a tumor promoter, potential prognostic indicator, and therapeutic target of ESCC, which may play a role in regulating cell cycle progression." (PMID 36090903, 2022). "In vitro experiments, mouse xenograft tumors model also confirmed that down-regulation of CKAP2L could inhibit tumor growth, and overexpression of CKAP2L promoted tumor growth." (PMID 36090903, 2022). "The expression of CCNA2 and CKAP2L showed positive association with infiltrating levels of B cells, CD8+ T cells, CD4+ T cells, neutrophils, macrophages, and dendritic cells, but were weakly positive with tumor purity." (PMID 33927744, 2021). "However, the relationship between CKAP2L and tumor progression and prognosis in other tumors remains unclear." (PMID 37225919, 2023). "Hence, each grade of the tumor is heterogeneous and mixed with good and bad prognosis cases, which might express different levels of CKAP2L and consequently, a large error bar." (PMID 33375517, 2020). "Our previous research screened four genes from ENZ-resistant C4-2B cells, which were CCNA2, CKAP2L, NCAPG, and NUSAP1, and confirmed that the protein levels of these four genes also remained higher in ENZ-resistant xenograft tumor tissues." (PMID 34746227, 2021). "Nevertheless, the relationship between CKAP2L and tumor immune correlates is still not clearly articulated." (PMID 37225919, 2023). "Moreover, after subdividing the dataset according to tumor grade (Gr-II, Gr-III, and Gr-IV), CKAP2L mRNA expression significantly differed among the groups (p < 0.0001)." (PMID 33375517, 2020).
CKAP2L also shares sentences with these, for which no sentence is quoted: bladder cancer (3 papers); clear cell renal carcinoma (2); head and neck cancer (2); liver cancer (2); non-small cell lung carcinoma (2); ovarian carcinoma (2); acute myeloid leukemia (1); alcohol dependence (1); cervical cancer (1); colon cancer (1); endometrial cancer (1); esophageal cancer (1); gastric cancer (1); infection (1); kidney cancer (1); lymphoma (1); melanoma (1); pancreatic cancer (1).